NUPR1 (nuclear protein 1, transcriptional regulator)
Description:
Transcription regulator that converts stress signals into a program of gene expression that empowers cells with resistance to the stress induced by a change in their microenvironment. Thereby participates in the regulation of many processes namely cell-cycle, apoptosis, autophagy and DNA repair responses. Protects pancreatic cancer cells from stress-induced cell death by binding the RELB promoter and activating its transcription, leading to IER3 transactivation. Negatively regulates apoptosis through interaction with PTMA. Inhibits autophagy-induced apoptosis in cardiac cells through FOXO3 interaction, inducing cytoplasmic translocation of FOXO3 thereby preventing the FOXO3 association with the pro-autophagic BNIP3 promoter. Regulates methamphetamine-induced apoptosis and autophagy through DDIT3-mediated endoplasmic reticulum stress pathway (By similarity). Participates in DNA repair following gamma-irradiation by facilitating DNA access of the transcription machinery through interaction with MSL1 leading to inhibition of histone H4' Lys-16' acetylation (H4K16ac). Coactivator of PAX2 transcription factor activity, both by recruiting EP300 to increase PAX2 transcription factor activity and by binding PAXIP1 to suppress PAXIP1-induced inhibition on PAX2. Positively regulates cell cycle progression through interaction with COPS5 inducing cytoplasmic translocation of CDKN1B leading to the CDKN1B degradation. Coordinates, through its interaction with EP300, the association of MYOD1, EP300 and DDX5 to the MYOG promoter, leading to inhibition of cell-cycle progression and myogenic differentiation promotion. Negatively regulates beta cell proliferation via inhibition of cell-cycle regulatory genes expression through the suppression of their promoter activities (By similarity). Also required for LHB expression and ovarian maturation (By similarity). Exacerbates CNS inflammation and demyelination upon cuprizone treatment (By similarity).
Synonyms: COM1; p8
Tractability: No criterion of Open Targets' tractability assessment is met for any kind of drug.
Gene: Protein-coding gene on chromosome 16 (28,532,708 to 28,539,038, reverse strand). Ensembl gene ENSG00000176046.
Subcellular location: Nucleus; Cytoplasm; Cytoplasm, perinuclear region
Subcellular location (Human Protein Atlas): Nucleoplasm; Cytokinetic bridge
Gene Ontology:
Molecular function: DNA binding; protein binding; transcription coactivator activity; acetyltransferase activator activity; chromatin binding
Biological process: negative regulation of apoptotic process; negative regulation of autophagosome assembly; negative regulation of autophagy; negative regulation of cardiac muscle cell apoptotic process; negative regulation of cell cycle; negative regulation of glycolytic process; negative regulation of programmed necrotic cell death; positive regulation of cell cycle; positive regulation of intrinsic apoptotic signaling pathway; positive regulation of oxidative phosphorylation; positive regulation of proteasomal protein catabolic process; regulation of response to endoplasmic reticulum stress; negative regulation of cell population proliferation; negative regulation of epithelial cell apoptotic process; negative regulation of epithelial cell proliferation; negative regulation of type B pancreatic cell proliferation; positive regulation of neuroinflammatory response; positive regulation of neuron apoptotic process; regulation of autophagy; positive regulation of DNA-templated transcription
Cellular component: cytoplasm; nucleoplasm; nucleus; perinuclear region of cytoplasm; protein-DNA complex
Genetic constraint (gnomAD): Loss-of-function variants: 8 observed, 7.72 expected, observed/expected ratio (o/e) 1.04, 90% interval 0.6 to 1.75. That is too few expected variants to judge how well the gene tolerates losing a copy. Missense variants: 96 observed, 117.44 expected, observed/expected ratio (o/e) 0.82, 90% interval 0.69 to 0.97. Synonymous variants: 39 observed, 46.46 expected, observed/expected ratio (o/e) 0.84, 90% interval 0.65 to 1.1.
Homologues: Orthologues: chimpanzee NUPR1 (98% identical), dog NUPR1 (85% identical), pig NUPR1 (78% identical), guinea pig NUPR1 (72% identical), rat Nupr1 (72% identical), mouse Nupr1 (71% identical), rabbit NUPR1 (71% identical), tropical clawed frog nupr1 (44% identical), zebrafish nupr1b (40% identical), Drosophila melanogaster CG6770 (28% identical). Paralogues in human: NUPR2 (43% identical).
Diseases named in the same sentence as NUPR1 in open-access papers:
NUPR1 is named in the same sentence as 97 diseases in open-access papers, as found by Europe PMC text mining. Sharing a sentence is not in itself a finding about the gene and the disease. The quoted sentences say what the papers report.
breast cancer (38 papers, 2012 to 2026). A primary or metastatic malignant neoplasm involving the breast. "Previous work has indicated that the loss of NUPR1 suppresses tumor progression by inducing premature senescence and ferroptosis in breast cancer." (PMID 41429768, 2025). "It has been shown that NUPR1 is associated with poor prognosis as well as chemoresistance in breast cancer." (PMID 34370741, 2021). "Collectively, these findings suggest a critical role for NUPR1 as a transcriptional coregulator in enabling endocrine persistence of breast cancers, thus providing a vulnerable diagnostic and/or therapeutic target for endocrine resistance." (PMID 33542201, 2021). "Collectively, these data indicate that NUPR1 depletion renders TamR breast cancer cells more susceptible to premature senescence and cytoplasmic vacuolization." (PMID 33542201, 2021). "Interestingly, NUPR1, a gene associated with tamoxifen resistance in breast cancer cells, was predicted to be inhibited in IPA." (PMID 40531193, 2025). "Furthermore, gene analysis between domains 2 and 0 indicate that NUPR1 is upregulated, which is linked to chemotherapy resistance of breast cancer." (PMID 38783355, 2024). "NUPR1 is a stress response protein frequently amplified in breast cancer; whilst it has a large set of varied roles in the cell, its expression has been associated with progression and chemoresistance in breast cancer." (PMID 30670058, 2019). "Nupr1, also known as p8 or candidate of metastasis-1 (Com-1), is a basic helix-loop-helix transcription co-factor strongly induced by stress (for review, Cano & Iovanna, 2010) and upon stimulation by TGFβ, which was associated to metastasis potential of breast cancer cells." (PMID 22821859, 2012). "Significant upregulation of NUPR1 was observed in brain metastasis of breast cancer and oral squamous cell carcinoma." (PMID 39085744, 2025). "At the molecular level, we discovered NUPR1 as a positive expression regulator of HDAC5 in breast cancer cells." (PMID 39991577, 2025). "Here, NUPR1 siRNA treatment also decreased the viability of the NUPR1 highly expressing SK-BR-3 breast cancer cells." (PMID 39991577, 2025). "Differentially expressed genes (DEGs) such as KRT8 and KRT18, associated with epithelial function, were highly expressed in these domains, while NUPR1, a prognostic marker in early-stage breast cancer, was upregulated." (PMID 40838787, 2025). "High NUPR1 expression levels have been identified in various cancers including oral squamous cell carcinoma, breast cancer, lung cancer, multiple myeloma, liver cancer and kidney cancer." (PMID 40176685, 2025). "Among them, we had successively discovered the crucial roles of the autophagy-lysosome and premature senescence pathway regulated by NUPR1 in non-small cell lung cancer and the drug resistance of ER+ breast cancer." (PMID 41429768, 2025). "Here, we found that the ER+ MCF7-derived endocrine therapy-resistant MCF7-TamC3 breast cancer cells exhibit increased expression of an intrinsically disordered chromatin protein, NUPR1, compared to the parental luminal-A subtype like MCF7 breast cancer cells." (PMID 39991577, 2025). "Results of the bioinformatics analysis showed that the NUPR1 mRNA expression level is also correlated with the clinical grading of the Tamoxifen-treated ER+ primary breast cancer." (PMID 39991577, 2025). "Importantly, the elevated NUPR1 expression has been implicated in tumor progression, therapy-induced resistance, and poor clinical outcomes in pancreatic cancer, oral squamous cell carcinoma, lung cancer, liver cancer, renal cancer, and breast cancer, emerging as a promising therapeutic target." (PMID 41429768, 2025). "Next, we sought to determine if NUPR1 upregulation readily promotes endocrine therapy resistance in ER+ breast cancer." (PMID 39991577, 2025).
breast cancer (continued). "Given the critical role of NUPR1 in breast cancer, we next developed a high-throughput screening platform for sdAbs targeting NUPR1, aiming to provide a new therapeutic approach for TNBC." (PMID 41429768, 2025). "In breast cancer cells, NUPR1 upregulates p21 transcription, allowing breast cancer cells to progress through the cell cycle, and it confers resistance to chemotherapeutic agents such as taxol and DOX." (PMID 38536720, 2024). "Various breast cancer cell lines that were classified as positive for estrogen receptor (ER+) and TNBC demonstrated elevated NUPR1 mRNA and protein compared to non-breast cancer cells." (PMID 38405101, 2024). "Nuclear protein 1 (NUPR1), which is associated with metastasis in mice, is upregulated in breast cancer cells and tissues." (PMID 36831154, 2023). "In stratification analysis based on the cancer stage, the expression of NUPR1 was augmented in more advanced breast cancer." (PMID 36468653, 2023). "Previous studies have explored the dysregulation of NUPR1 in numerous malignant tumors, such as brain tumors, lung cancer, breast cancer, colorectal cancer, and prostate cancer." (PMID 36468653, 2023). "On the other hand, in breast cancer, renal clear cell carcinoma, and liver cancer, the expression of NUPR1 was increased." (PMID 37626099, 2023). "Here, we investigate how NUPR1 accelerates and maintains the development of Tam-induced resistance in breast cancer cells, and what this means in relation to enhancing antiestrogen therapy." (PMID 33542201, 2021). "Lastly, to further elucidate the role of NUPR1 in breast cancer, we assessed the transcriptional profile of the affected genes upon NUPR1 depletion using RNA sequencing." (PMID 33542201, 2021). "In another study, NUPR1 transcriptionally activated the presynaptic ROS sensor synaptosome associated protein 25 (SNAP25) and maintained the autolysosomal efflux in breast cancer cells." (PMID 34359572, 2021). "In Tam-resistant ESR1 breast cancer cells, NUPR1 depletion results in premature senescence in vitro and tumor suppression in vivo." (PMID 33542201, 2021). "High NUPR1 protein level was a strong predictor of low survival rates in breast cancer patients (hazard ratio 6.998, CI 4.128–11.862)." (PMID 33542201, 2021). "Taken together, these data indicate that NUPR1 depletion overcomes Tam resistance in breast cancer cells." (PMID 33542201, 2021). "In endocrine therapy resistant breast cancer cells, ESR1 associates with the transcriptional regulator NUPR1 and regulates the transcription of their targets, resulting in enhanced autophagic survival and more malignant behavior." (PMID 33542201, 2021). "NUPR1 dysregulation has been reported in several malignancies, including breast cancer, pancreatic cancer, lung cancer, prostate cancer, colorectal cancer and glioma." (PMID 34030133, 2021). "Taken together, these findings demonstrate that NUPR1 is a novel participant in the development of Tam resistance that maintains breast cancer cells at an elevated autolysosomal state through ESR1-mediated transcription." (PMID 33542201, 2021). "Of 133 subjects of breast cancer tissues, medium survivals were 95.4 months with low NUPR1 staining score (n = 91) and 68.1 months with high NUPR1 scores (n = 42, P = 0.0021)." (PMID 33542201, 2021). "Nupr1 expression was also much lower in human ovarian cancer cells (A2780) and human breast cancer cells (MCF-7) cultured in 3D soft fibrin gels, suggesting that low mRNA expression of Nupr1 is not limited to melanoma cells in 3D soft substrates." (PMID 27089143, 2016). "Although the NUPR1 gene has been suggested to be responsible for the growth and progression of many cancers including breast cancer, the prognostic implications of the NUPR1 gene in EBC have not been reported." (PMID 22938721, 2012).
breast cancer (continued). "We noticed that the ERBB2 (HER2)-enriched subtype-like [ER-, ERBB2 (HER2)+/high] SK-BR-3 breast cancer cells express a large amount of the nucleic NUPR1 protein endogenously, as compared to MCF7 and MCF7-TamC3 cells, and the si-NUPR1 treatment also decreased the expression of HDAC5 in SK-BR-3 cells." (PMID 39991577, 2025). "Kaplan–Meier analysis showed that high NUPR1 expression was also strongly associated with a poor prognosis in ER and PR negative breast cancer patients." (PMID 41429768, 2025). "In this part, we found that our designed sdAb#07.81 could not only directly bind to NUPR1 but also enter cells to exert its inhibitory functions against breast cancer cells." (PMID 41429768, 2025). "Upregulation of NUPR1 can be found in the ER+, estrogen-independent, tamoxifen-resistant breast cancer cells and high mRNA expression of NUPR1 correlates with poor clinical outcomes in ER+ endocrine therapy-treated breast cancer patients." (PMID 39991577, 2025). "Targeting NUPR1 or its downstream regulating molecules may offer a potential strategy for overcoming resistance to endocrine therapy in patients with ER+ breast cancer." (PMID 39991577, 2025). "Re-biopsy of tumor tissues to assess the real-time status of ERBB2 expression in endocrine therapy-resistant ER+ breast cancer may be necessary for the decision to use Trastuzumab Deruxtecan, particularly in cases of NUPR1-overexpressing breast tumors." (PMID 39991577, 2025). "Like breast cancer, colon cancer metastasis is also driven by elevated NUPR1." (PMID 38405101, 2024). "Interestingly, we also found that NUPR1 depletion in MCF-7TamR cells resulted in decreased pro-migratory cytokine interleukin-6 (IL-6) production, suggesting a role for NUPR1 in the induction of IL-6 expression in Tam resistant breast cancer cells." (PMID 33542201, 2021). "In addition, NUPR1-depleted breast cancer cells show defects in autophagic degradation, resulting in premature senescence and reduced malignancy in vitro and in vivo." (PMID 33542201, 2021). "Based on these findings, we suggest that the elevated NUPR1 protein level may provide a novel biomarker for Tam resistance in ESR1-positive breast cancer cells." (PMID 33542201, 2021). "Targeting the NUPR1-mediated autophagic regulation may render ESR1-positive breast cancer cells more sensitive to antiestrogen therapy." (PMID 33542201, 2021). "At present, we found that the level of NUPR1 is higher in a subpopulation of endocrine therapy resistant breast cancer cells than that in parental breast cancer cells, presumably through the elevated autophagic process induced by NUPR1-mediated transcription regulation." (PMID 33542201, 2021). "Since Tam induces NUPR1 transcription, NUPR1 depletion may be detrimental to TamR breast cancer cells." (PMID 33542201, 2021). "Moreover, Tam treatment induced NUPR1 expression at a consistent level in a time-dependent and dose-dependent manner in three ERα-positive breast cancer cell lines, which are TamR after 15 months of treatment." (PMID 33542201, 2021). "Similarly, NUPR1 has been found to be highly expressed in breast cancer cells." (PMID 40362379, 2025). "Indeed, previous studies have also found that the silencing of NUPR1 down-regulates runt-related transcription factor 2 (RUNX2), a protein that is highly sensitive to iron overload, and ultimately causes premature senescence in breast cancer cells." (PMID 34359572, 2021). "Kaplan-Meier analysis of expression cohorts of breast tumors showed that high NUPR1 mRNA expression levels correlate with poor overall and relapse-free survival in both endocrine therapy-treated ER+ and ERBB2-enriched breast cancer patients." (PMID 39991577, 2025). "Taken together, these results indicate that NUPR1 positively regulates the expression of ERBB2 and promotes the EGF-ERBB2 pathway-related survival in breast cancer cells." (PMID 39991577, 2025).